AKT1 (AKT serine/threonine kinase 1)
Diseases named in the same sentence as AKT1 in open-access papers (continued):
Sharing a sentence is not in itself a finding about the gene and the disease.
type 2 diabetes (105 papers, 2011 to 2026). "As an example we demonstrated conservation of human hsa-miR-143-3p which is associated with type 2 diabetes and targets AKT1 gene which is highly conserved in pig, horse and dog." (PMID 24970281, 2014). "However, haplodeficiency of Akt1 in Akt2-null mice exacerbates their insulin resistant phenotype to cause overt type 2 diabetes, thereby suggesting that Akt1 might also contribute to sustain glucose homoeostasis in mice." (PMID 25856301, 2015). "Akt1 isoform is considered a kinase favorable for early myogenic differentiation and its dysregulation plays a role in muscle atrophy and diabetes type II-related sarcopenia." (PMID 36139434, 2022). "MAPK3, and AKT1 were involved in Insulin signaling pathway (hsa04910), and Type II diabetes mellitus (hsa04930)." (PMID 34017037, 2021). "These include LOAD risk-associated gene Cathepsin D (FDR = 4.9E−02), and Akt1 (FDR = 6.8E−04), a molecule that is activated in LOAD and is associated with LOAD risk in Chinese Han AD patients with type 2 diabetes." (PMID 28612290, 2017). "Apparently, high-fat diet-induced type 2 diabetes in C57BL/6J mice has defective peripheral glucose utilization due to deficiency in IRS-1, resulting in downstream defect in Akt-1-PI-3 kinase activation." (PMID 21785636, 2011). "In Drosophila type 2 diabetes models can be generated by two different strategies: by downregulating conserved genes working on insulin pathways as for example the insulin receptor InR, the insulin substrate receptor chico/IRS1, Akt1, PI3K, and by feeding flies with a high sugar rich diet." (PMID 30271425, 2018).
breast tumors (101 papers, 2005 to 2025). "Almost all (94.3%, 33/35) of AKT1 mutations were identified in HR+/HER2- breast tumors, with only one typical hotspot mutation." (PMID 34093841, 2021). "The majority (94.3%, 33/35) of AKT1 mutations were detected among patients with HR+/HER2- breast tumor." (PMID 34093841, 2021). "Deleterious mutations in GATA3, an activating SF3B1 mutation (K700E), and an activating AKT1 mutation (E17K) were observed in eight (16.7%), three (6.3%), and three (6.3%) breast tumors, respectively." (PMID 29464067, 2018). "Once established that Vav1 modulates the activation of Akt1 in breast tumor‐derived cells, we investigated the association between the Vav1/p‐Akt (Ser473) levels and the clinical outcome of breast cancer patients." (PMID 29658179, 2018). "We further explored the possible role of Vav1 in modulating Akt2, whose expression is phenotype‐dependent and whose role in breast tumors seems to be different from that of Akt1 and mainly associated with migration and metastasis." (PMID 29658179, 2018). "Recently, it was reported that MRK-003 GSI treatment of Balb/c-neuT female mice reduced tumour onset, tumour burden, and AKT1/mTOR activities associated with ErbB-2-positive, murine breast tumours." (PMID 21847123, 2011). "Specifically, we analyzed Akt1 and Akt2, the two isoforms most closely related to invasiveness in breast tumors and that we found modified by garlic extract in other breast tumor cells." (PMID 41228363, 2025). "The TNBC cell lines under investigation were then treated with garlic extract and first subjected to immunochemical analysis of the expression and activation status of Akt1 and Akt2, the most studied isozymes in breast tumors." (PMID 38786044, 2024). "Further, previous studies have shown cytoplasmic localization of PELP1 occurs in breast tumors and contributes to endocrine resistance via Akt1 activation." (PMID 35395812, 2022). "A recent study showed that inhibition of PI3K or AKT1 reduces the frequency of BTIC-enriched CD44High/CD24Low breast tumor cells by initiating their apoptosis via FOXO3a and Bim." (PMID 32758183, 2020). "The decreased p‐Akt1 (Ser473) levels are a common effect of Vav1 upmodulation, suggesting that, in breast tumor‐derived cells and independently of their phenotype, Vav1 interferes with signaling pathways ended to specifically recruit Akt1." (PMID 29658179, 2018). "AKT1 also showed significant hypo-methylation in breast tumor tissues in TCGA, which is consistent with our results." (PMID 28301567, 2017). "Sequencing of bisulfite-converted genomic DNAs revealed that the AKT1 promoter region were hypo-methylated in breast tumor tissues compared with the matched adjacent normal tissues." (PMID 28301567, 2017). "Another well-studied cancer mutation we identify is the substitution E17K in AKT1 (PKB) kinase of the PI3K pathway, observed across 20 samples including 18 breast tumors." (PMID 27175787, 2016). "The nature of these genetic lesions remains to be determined, but are not likely to include oncogenic PIK3CA mutations or PTEN inactivation, which have been shown to be mutually exclusive with AKT1(E17K), at least in breast tumors." (PMID 27004402, 2016). "Although both AKT1 and AKT2 are required for breast tumor growth, AKT1 appears to suppress, while AKT2 promotes tumor metastasis." (PMID 26895380, 2016). "PTEN loss occurring in up to 30% of unselected breast tumor cohorts is also predominantly mutually exclusive with PIK3CA and AKT1 mutations." (PMID 24229379, 2013). "High BRCA1-IRIS expression was detected in the majority of human breast tumors analyzed, which was positively correlated with that of AKT1-, AKT2-, p-AKT-, survivin, but negatively with BRCA1/p220 expression." (PMID 22511931, 2012).
breast tumors (continued). "To examine the validity of this hypothesis, we performed a multivariate analysis of AKT1 overexpression in conjunction with 10 highly abundant AKT-dependent transcripts on the overall disease-free survival of patients with breast tumors." (PMID 35892586, 2022). "One point four percentage AKT1 mutation and 2.3% PTEN mutations were limited to HR+ breast tumors." (PMID 34769309, 2021). "Indeed, the TRIB3/AKT1 interaction was abrogated in MMTV-PyMT MEC-derived breast tumors and PDX breast tumors." (PMID 31844113, 2019). "This may contribute to the distinct ability of Akt1 to promote breast tumor initiation and impair invasion and migration, while Akt2 enhances the invasive and metastatic capabilities of breast tumors." (PMID 31131274, 2019). "Overall, our data indicate that, in breast tumor‐derived cells with different phenotypes, the sole modulation of Vav1 is sufficient to affect the activation status of Akt1, involved in the insurgence and growth of breast tumors, but not of Akt2, mainly responsible of tumor metastasis." (PMID 29658179, 2018). "AKT1 expression was elevated in 14 and reduced in 9 breast tumors." (PMID 28301567, 2017). "Furthermore, AKT1(E17K) has been found predominantly in estrogen receptor (ER)-positive breast tumors." (PMID 27004402, 2016). "A recent study also showed that AKT2 but not AKT1 is required for the maintenance of PTEN-deficient breast tumor spheroids in 3D culture." (PMID 26895380, 2016). "In addition to doxorubicin, puromycin was applied to Akt1+/+ and Akt1−/− breast tumor cells to analyze the induced cellular apoptosis." (PMID 24658544, 2014). "It has been demonstrated that Pep2–Ae binding to TRIB3 enhanced the activity of AKT1 in MEC- and PDX-derived breast tumors." (PMID 38731938, 2024). "The levels of TMEM213 were found to be upregulated upon silencing AKT1 (this study), and an inverse correlation exists between the levels of AKT1 and TMEM213 in breast tumors." (PMID 35892586, 2022). "In conclusion, AKT1 and RPS6KB2, two important prognostic predictors in the mTOR pathway, are expressed differently in breast tumors in Black and White women." (PMID 35608730, 2022). "In multivariable models, Black women had relative under-expression of AKT1 (log2 fold-change = − 0.31, 95% CI − 0.44, -0.18) and RPS6KB2 (log2 fold-change = − 0.11, 95% CI − 0.19, − 0.03) in their breast tumors compared to White women." (PMID 35608730, 2022). "Vav1 is ectopically expressed in breast tumor cells, including TNBC derived cells, in which it promotes the down-modulation of activated Akt1, resulting in reduced tumor growth in vivo." (PMID 35743776, 2022). "We therefore derived breast tumor cell lines from MMTV-ErbB2/Akt1−/− and MMTV-ErbB2/Akt1+/+ litter mate control mice and thereby assessed the role of Akt1 in miR-17/20 mediated apoptosis." (PMID 24658544, 2014). "The up-regulated genes include CTNNB1, GSC and TWIST1, encoding for transcription factors known to be activated during breast tumor metastasis, and AHNAK and AKT1, variously involved in tumorigenesis and cell motility." (PMID 24962430, 2014). "We confirmed that Akt1 and Akt2 are widely expressed in HER2-positive breast tumours and, simultaneously, tumours contain their activated form." (PMID 22842582, 2012).
breast tumors (continued). "HER2-low breast tumors had significantly more frequent mutations in phosphatase and tensin homolog (PTEN; p < 0.001), GATA binding protein 3 (GATA3; p < 0.001), core-binding factor subunit beta (CBFB; p < 0.001), and AKT serine/threonine kinase 1 (AKT1; p < 0.001) than HER2-positive breast tumors." (PMID 35484593, 2022). "Studies from transgenic mice suggested that Akt1 plays an important role in the initiation, development, and progression of breast tumors, whereas Akt2 has no major involvement in the process of tumor initiation but contributes to the process of tumor growth." (PMID 35892586, 2022). "Finally, Pep2–Ae enhanced the activity of AKT1 and FOXO1, and reduced the expression of FOXO1 and SOX2 in MMTV-PyMT MEC-derived breast tumors and PDX-derived breast tumors." (PMID 31844113, 2019). "The study included both in vitro and in vivo models in which the effects of forcedly modulated Vav1 on the main Akt1‐related pathways were investigated primarily in breast tumor cells with a triple‐negative phenotype." (PMID 29658179, 2018). "The ability of Vav1 to downmodulate p‐Akt1 is not restricted to cells with a triple‐negative phenotype, as we revealed by modulating Vav1 in cell lines representing the most frequent breast tumor subtypes." (PMID 29658179, 2018). "In the present study, AKT1 was significantly hypo-methylated and less expressed in the breast tumor compared with the matched normal tissue, but no significant cis correlation was found between methylation and expression." (PMID 28301567, 2017). "And a trend of decrease in expression level (P = 0.0624) of AKT1 in the ER negative subtype was observed, which is significantly decreased in basal-like breast tumor (P = 0.0328)." (PMID 28301567, 2017). "Immunohistochemical staining of large cohort of human breast tumor samples using new monoclonal anti-BRCA1-IRIS antibody, followed by correlation of BRCA1-IRIS expression with that of AKT1, AKT2, p-AKT, survivin and BRCA1/p220, tumor status and age at diagnosis." (PMID 22511931, 2012). "We found that depletion of AKT1 leads to upregulation of a subset of genes—many of which are also found to be downregulated in breast tumors with elevated high AKT1 as well as upregulated in breast tumors with no detectable AKT expression." (PMID 35892586, 2022). "As AKT1 has been shown to be overexpressed and/or hyperactivated in breast tumors, our results imply that many downstream phenotypic effects of AKT are not merely mediated by AKT1-signaling dependent phosphorylation of its direct substrates but also by genomic effects of AKT1." (PMID 35892586, 2022). "Therefore, the activated pAkt in breast tumors in our patient cohort determined by IHC may not be limited to phosphorylation of Akt1 or Akt2 only." (PMID 18184439, 2008).
neuroblastoma (96 papers, 2008 to 2025). Neuroblastoma (NB) is the most common solid, extracranial childhood tumor. "Though the Akt1/Akt2 ratio was found to regulate expression of miR-200 and miR-182 in a neuroblastoma cell line, and modulation of these miRNAs caused differential expression of EMT-related proteins, whether this is the case in hibernating TLGS remains inconclusive." (PMID 29440989, 2018). "Based on our findings we propose that targeting PRMT5 will limit AKT1 activation, metastases, and drug resistance of neuroblastoma and other aggressive cancers." (PMID 35803962, 2022). "HA-tagged AKT-wild type or AKT1-R15K were immunoprecipitated from transfected neuroblastoma cells and analyzed by western blotting for PDK1 and SIN1." (PMID 35803962, 2022). "Terpinolene down-regulates AKT1 expression in K562 cells and reveals inhibitory effects in N2a neuroblastoma cells." (PMID 34151367, 2021). "The main Akt1 molecule was found in neuroblastoma cells at pI 5.53, in cortical neurons at 5.42, and in brain lysate at 5.61." (PMID 26945062, 2016). "In addition, PRMT5 methylates AKT1 on Arg 15 in the PH domain, promoting AKT1 translocation to the plasma membrane and subsequent phosphorylation at Thr308 and Ser473 in neuroblastoma." (PMID 36499164, 2022). "HA-tagged AKT1 wild-type or R15K mutant constructs were transfected into neuroblastoma cells." (PMID 35803962, 2022). "While testing the potential of AKT1-R391 being a substrate of PRMT5 in neuroblastoma, we found that the ectopic expression of AKT1-R391K mutant is significantly lower compared to AKT1 wild type and R15K mutant even in the presence of proteasome inhibitor MG132." (PMID 35803962, 2022). "To determine whether OXPHOS represents a survival metabolic pathway active in neuroblastoma cells with inhibited kinase Akt‐1/2 and glucose uptake, we addressed the cytotoxic effect of Akti‐1/2 in combination with mitochondrial inhibitors." (PMID 28244639, 2017). "A detailed characterization based on Akt isoform antibodies and phosphatase experiments in neuroblastoma cells suggested that the peaks with pI 5.06, 5.14, and 5.31 correspond primarily to Akt1, whereas peaks with pI 5.42, and 5.53 correspond to mixed Akt isoforms, most likely Akt1 and Akt2." (PMID 26945062, 2016). "In neuroblastoma cells, this latent form may even exert beneficial effects, blocking apoptosis and promoting neurite extension via AKT1 upregulation." (PMID 22254144, 2011). "In GSK591-treated neuroblastoma cells, SDMA, as well as phosphorylation on endogenous AKT1 was markedly decreased." (PMID 35803962, 2022). "miR-149* is known to induce apoptosis by the direct inhibition of Akt1 and E2F1 in neuroblastoma cells." (PMID 22682234, 2012). "In this study, we found that silencing AKT2, but not AKT1 or AKT3 suppresses N-myc expression in neuroblastoma cells." (PMID 23468863, 2013). "The other isoform which is expressed at high levels in neuroblastoma cell lines, AKT1, does not possess a miR-184 target site, remains constant in all of our experiments, and does not rescue the cells from the effects of miR-184 over-expression." (PMID 20409325, 2010). "Interestingly, silencing AKT2, but not the AKT1 isoform, significantly increased Gli1 luciferase activity in both human neuroblastoma cell lines examined, thus demonstrating negative regulation of Gli1 by AKT2." (PMID 23900341, 2013). "Since, GRP-R silencing specifically inhibited the expression of AKT2 isoform, but not AKT1 or AKT3, we can further conclude that GRP-R-mediated regulation of N-myc expression in neuroblastoma cells is AKT2-dependent." (PMID 23468863, 2013). "Moreover, GRP-R modulates N-myc expression in neuroblastoma cells by AKT2 isoform, but not the AKT1 or AKT3." (PMID 23468863, 2013). "Interestingly, silencing GRP-R predominantly reduces AKT2 expression without affecting the expression of AKT1 or AKT3 isoform, thus demonstrating a more critical role of AKT2 in GRP-R-mediated neuroblastoma tumorigenesis." (PMID 23468863, 2013).